WNT5A (Wnt family member 5A)
Diseases named in the same sentence as WNT5A in open-access papers (continued):
Sharing a sentence is not in itself a finding about the gene and the disease.
Ewing sarcoma (continued). "Several of these Ewing sarcoma tumor cell–expressed genes have been previously studied in Ewing sarcoma [AXL, WNT5A, IGF-1R, TNFRSF10B (TRIAL-R2/DR5)], and have been described as potential targets in Ewing sarcoma and/or to be involved in Ewing sarcoma tumor cell migration/metastatic potential." (PMID 37823774, 2023). "Our data demonstrate that a lack of Wnt5a in Ewing sarcoma cells affects cell migration and the phenotypic changes of the Wnt5a knock-out clones as well as the fact that they require a matrix of fibronectin to adhere well is consistent with the function of focal adhesions." (PMID 41301074, 2025). "Changes in N-glycosylation of ALCAM in Wnt5a knock-out cells may suggest that post-translational modifications might affect Ewing sarcoma cell migration as the Wnt5a knock-out clones do not migrate well." (PMID 41301074, 2025). "To test this hypothesis, we treated Ewing sarcoma cell lines with WNT974 to inhibit production of all endogenous Wnt ligands and then added exogenous recombinant Wnt5a to determine if the transcriptional changes are a direct result of Wnt5a in the microenvironment." (PMID 41301074, 2025). "WNT974 does not alter phalloidin staining in the Wnt5a knock-out clones, providing additional support that this non-canonical Wnt ligand is the key mediator of the phenotypic effects of WNT974 on Ewing sarcoma cells." (PMID 41301074, 2025).
fatty liver (3 papers, 2014 to 2025). "Since it was reported that the noncanonical WNT pathway involving JNK activation had been implicated in fatty liver disease, we wanted to study the hepatic relative mRNA expression of WNT5A and JNK to add new knowledge about the role of this pathway in NAFLD pathogenesis." (PMID 34198988, 2021).
head and neck squamous cell carcinoma (3 papers, 2018 to 2024). A squamous cell carcinoma that arises from any of the following anatomic sites: lip and oral cavity, nasal cavity, paranasal sinuses, pharynx, larynx, and salivary glands. "Although Wnt5a has been associated with tumor progression and autophagy, the study of radiation therapy resistance of Wnt5a in head and neck squamous cell carcinoma is unclear." (PMID 35517407, 2022). "In the literature, Wnt5a has been reported to have the specificity of tumor activity (differentiation, proliferation, and invasion) 46 in head and neck squamous cell carcinoma." (PMID 35517407, 2022). "By mining the TCGA-HNSC (the Cancer Genome Atlas- Head and Neck Squamous Cell Carcinoma) database, although none of the three ligands had prognostic value, we found that Wnt5a was significantly upregulated in head and neck squamous cell carcinoma." (PMID 35517407, 2022). "DACT, WNT5A, and WNT7B were significantly positive correlation with TET1(p < 0.05), and WNT4 and WNT7A were negative correlation with TET1 in the TCGA Head and Neck Squamous cell Carcinoma database (p < 0.05)." (PMID 30075814, 2018).
Infertility (3 papers, 2014 to 2020). "As previously reported, conditional deletion of Wnt5a with an Amhr2-driver caused infertility and impairment of ovulation." (PMID 32546756, 2020). "For examples, deficiency in the Wnt signaling, including in Wnt4, Wnt5a, and Wnt7a, will result in severe malformation of the genitals and infertility, whereas hyperactivation of the Wnt/β-catenin pathway can also lead to germ cell apoptosis and male infertility." (PMID 25188337, 2014).
inflammatory bowel disease (3 papers, 2011 to 2015). A spectrum of small and large bowel inflammatory diseases of unknown etiology. "Taken together, these results suggest that fibroblasts might be the primary source of Wnt5a at least in the colon during inflammatory bowel disease." (PMID 26030277, 2015). "Wnt5a was highly expressed in stromal fibroblasts in ulcerative lesions in the DSS-treated mice and inflammatory bowel disease patients." (PMID 26030277, 2015).
intestinal cancer (3 papers, 2016 to 2023). "In intestinal cancer, overexpression of Wnt5a inhibited cell proliferation and diminished tumorigenicity in nude mice models through down-regulating the expression of c-Myc." (PMID 27571105, 2016).
keloid (3 papers, 2016 to 2025). An irregularly shaped, elevated mark on the skin caused by deposits of excessive amounts of collagen during wound healing. "Subsequently, three of these genes (BMP4, POSTN, and WNT5A) were found to be significantly associated with keloids." (PMID 41278551, 2025). "We found that the expression levels of BMP4, POSTN, and WNT5A were significantly higher in keloid samples compared to control samples, as identified through differential gene screening and validated using an independent dataset." (PMID 41278551, 2025). "Key hub proteins such as SMAD3, BMP4, and WNT5A are centrally positioned, suggesting their potential roles as critical regulators in keloid pathogenesis." (PMID 41278551, 2025). "The validation of the screened hub genes in the GEO dataset revealed that three hub genes—BMP4, POSTN, and WNT5A—were significantly differentially expressed in keloid tissue compared to normal skin tissue." (PMID 41278551, 2025). "POSTN and WNT5A demonstrated perfect discriminative ability with AUC values of 1.000, indicating their high specificity and sensitivity in identifying keloid tissue." (PMID 41278551, 2025). "In keloid scars, TGF-β1-induced overexpression in keloid keratinocytes of secreted factors, such as IL6 and WNT5A, may contribute to fibrosis directly, by stimulating signaling pathways in keloid fibroblasts that increase ECM production or indirectly by promoting an inflammatory microenvironment." (PMID 27574697, 2016). "Thus, WNT5A may serve as a critical link between inflammatory cues and structural remodeling in keloid progression, and the WNT5A signaling pathway may help develop new strategies for early intervention in keloid formation." (PMID 41278551, 2025). "Nevertheless, PPI network analysis and subsequent validation using the independent GSE158395 dataset consistently identified BMP4, WNT5A, and POSTN as top hub genes significantly upregulated in keloid tissues." (PMID 41278551, 2025). "In conclusion, our study identifies BMP4, WNT5A, and POSTN as novel and consistently upregulated hub genes in keloids, potentially acting at the nexus of mechanosignaling, inflammation, and matrix remodeling." (PMID 41278551, 2025). "Similarly, the expression of WNT5A was significantly increased in keloids (p < 0.01), suggesting its involvement in noncanonical Wnt signaling and cell migration." (PMID 41278551, 2025).
liver cancer (3 papers, 2016 to 2024). An epithelial or non-epithelial malignant neoplasm that arises from the liver. "To further explore the role of WNT5A in liver cancer, we treated primary liver cancer cells with WNT5A, and found WNT5A treated cells showed enhanced Wnt/β-catenin activation." (PMID 29535420, 2018). "We analyzed WNT expression profiles using online available data, and found WNT5A is highly expressed in liver cancer." (PMID 29535420, 2018). "Using primary HCC samples, we confirmed the high expression of WNT5A in liver cancer, especially in advanced liver cancer." (PMID 29535420, 2018). "In this study, we found that ZIP4 binds to Ephrin-B1 to inhibit the ubiquitination of Ephrin-B1, regulating the Wnt family member 5A (Wnt5A)/Jun N-terminal kinase (JNK)/ZEB1 signaling pathway and promoting EMT, thereby inducing invasion and metastasis of liver cancer cells." (PMID 39040931, 2024).
lymphoma (3 papers, 2013 to 2021). A malignant (clonal) proliferation of B- lymphocytes or T- lymphocytes which involves the lymph nodes, bone marrow and/or extranodal sites. "However, our results need to be confirmed in additional adult T-ALL cell lines and primary cells, and the specific role of Wnt5a in MOLT4 cell metastasis must still be investigated, and whether Wnt5a is related with T lymphomas metastasis is not clear, which is also worthy to be investigated." (PMID 28380463, 2017).
mantle cell lymphoma (3 papers, 2018 to 2022). Mantle cell lymphoma is a rare form of malignant non-Hodgkin lymphoma affecting B lymphocytes in the lymph nodes in a region called the ``mantle zone''. "In another study, NFκB p65 was identified as a downstream target of Wnt5a/ROR1, leading to drug resistance in mantle cell lymphoma (MCL)." (PMID 32751131, 2020). "Chronic lymphocytic leukemia (CLL) and mantle cell lymphoma (MCL) are malignancies characterized by the dependence on B-cell receptor (BCR) signaling and by the high expression of ROR1, the cell surface receptor for Wnt-5a." (PMID 35295854, 2022).
metastatic prostate carcinoma (3 papers, 2019 to 2021). A carcinoma that arises from the prostate gland and has spread to other anatomic sites. "Protein derived from Wnt5A gene (WNT5A) plays an important role in primary and metastatic prostate cancer (PCa)." (PMID 33639039, 2021). "It has been reported that the activation of the WNT5A/FZD2-induced noncanonical WNT pathway (NCWP) promotes the progression of advanced and metastatic prostate cancer and induces the epithelial-to-mesenchymal transition (EMT) in certain cancers." (PMID 31595151, 2019).
Myocardial fibrosis (3 papers, 2020 to 2022). "The aim of this study is to investigate whether the transcriptional factor paired‐related homeobox 2 (Prrx2) regulates Wnt5a gene expression and the role in myocardial fibrosis following MI." (PMID 31880857, 2020). "Previous in vitro experiments revealed that Wnt5a activates CFs and induces IL-6 and TIMP-1 synthesis, thereby promoting the occurrence of myocarditis and myocardial fibrosis." (PMID 36404310, 2022). "A recent study also showed that Wnt ligand (Wnt-1/Wnt-5a) secretion was a necessary downstream step for TGF-β–mediated myofibroblast differentiation and myocardial fibrosis in experimental autoimmune myocarditis." (PMID 33442383, 2020).
orofacial cleft (3 papers, 2019 to 2025). A disorder of facial skeleton that is characterized by cleft lip and/or cleft palate that result in feeding, speech and hearing problems caused by failures during development. "Associations between the WNT5A rs566926 variant and non-syndromic orofacial cleft (NSOC) have been reported in different populations." (PMID 38359266, 2024). "Wnt5a analogs, such as Foxy-5 or Box-5, currently used in cancer research, may also serve as a treatment approach for orofacial clefts by targeting non-canonical Wnt signaling, warranting future research." (PMID 30760477, 2019).
ovarian tumor (3 papers, 2016 to 2021). "An early study of primary ovarian tumors (n = 130) compared to normal ovarian surface or fallopian tube epithelium (n = 31 and 28, respectively) showed lower Wnt5a expression relative to normal tissue." (PMID 27571105, 2016). "Examination of data from 583 ovarian tumors show that Wnt5a is highly expressed." (PMID 27571105, 2016).
pancreatic adenocarcinoma (3 papers, 2013 to 2024). "Immunohistochemistry was performed to examine Wnt5a expression in 134 surgically resected pancreatic adenocarcinoma and adjacent normal pancreatic tissues." (PMID 24156409, 2013). "Recent evidence also suggests a functional relationship between YAP and Wnt5a in skin melanoma and pancreatic adenocarcinoma, two cancer types where a moderate correlation between YAP1 and WNT5A expression is observed." (PMID 33643710, 2021).
Peri-Implantitis (3 papers, 2021 to 2022). An inflammatory process with loss of supporting bone in the tissues surrounding functioning DENTAL IMPLANTS. "Instead of Wnt3A, Wnt5A expression was found to be upregulated in the gingival tissues with peri-implantitis." (PMID 35491409, 2022). "Wnt5a is also significantly upregulated in gingival tissues of peri-implantitis patients in response to Porphyromonas gingivalis." (PMID 34440994, 2021).
prostate tumour (3 papers, 2011 to 2024). "One of the most significant regions of differential methylation identified was an approximately 1 kb region within the WNT5A promoter, which was significantly demethylated in bone metastases when compared to primary prostate tumours." (PMID 39164966, 2024). "DNA methylation in the identified WNT5A region was further investigated in cell line models of primary prostate tumour and bone metastasis, 22Rv1 and PC‐3 cells, respectively." (PMID 39164966, 2024). "Silencing Wnt5a restored the growth ability of prostate tumour cells, indicating a potential therapeutic role of Wnt5a in preventing bone metastatic recurrence by inducing cancer cell dormancy." (PMID 36307871, 2022). "In addition, based on the determination of Wnt5a mRNA levels in prostate tumors it has been suggested that abnormal expression of the non-canonical Wnt5a is involved in PCa." (PMID 22039506, 2011).
serous ovarian cancer (3 papers, 2015 to 2022). "We drew the heatmap plot to classify the up-regulated and down-regulated analyzed genes including integrins, CDH-1, CDH-2, and Wnt5A in different subtypes of serous ovarian cancer and normal ovary." (PMID 33723319, 2021). "In line with these in vitro data, we found a positive relationship between Wnt5A and α5, αv, and β6 expression in the metastatic serous ovarian cancer groups." (PMID 33723319, 2021). "Wnt5A showed a positive correlation with TAZ and TGFβ1 in high- and low-grade serous ovarian cancer specimens compared to borderline serous and normal ovaries." (PMID 35053353, 2022). "We performed the qRT-PCR analysis of TGFβ components (TGFB1, TGFB2, TGFBR1, TGFBR2), Wnt5A/ROR1/ROR2, and Hippo-related genes (YAP1, TAZ, CCN1, and CCN2) in serous ovarian cancer subtypes (LGSOC, HGSOC, BLSOC) compared to the normal ovary." (PMID 35053353, 2022). "Accordingly, we observed significantly higher expression levels of ITGAV and ITGB3 in human high-grade serous ovarian cancer specimens and ITGAV correlated positively with Wnt5A in metastatic serous type ovarian cancer." (PMID 33723319, 2021). "Similar results were found when conducting ChIP on high-grade serous ovarian cancer cells (OVCAR3), with significant ARID3B binding found to Wnt5a, RIPK, BTC, and APC." (PMID 26121572, 2015).
skin cutaneous melanoma (3 papers, 2021 to 2024). "Additionally, it was shown that the expression of WNT5A in metastatic tissues of skin cutaneous melanoma (SKCM) was more significant than in tumor tissues of SKCM." (PMID 39176352, 2024).
spinal cord injury (3 papers, 2021 to 2026). Penetrating and non-penetrating injuries to the spinal cord resulting from traumatic external forces (e.g., WOUNDS, GUNSHOT; WHIPLASH INJURIES; etc.). "Accordingly to its known function in corticospinal tract (CST) developmental growth, previous reports have shown an inhibitory role of Wnt5a in CST regeneration after spinal cord injury (SCI)." (PMID 33939286, 2021).
acute kidney injury (2 papers, 2023 to 2024). Sudden and sustained deterioration of the kidney function characterized by decreased glomerular filtration rate, increased serum creatinine or oliguria. "This prospective study investigated the association between Wnt5a levels and persistent acute kidney injury (AKI) in patients with urosepsis." (PMID 38913943, 2024).
acute lymphoblast leukemia (2 papers, 2015 to 2016). "Here we show that WNT5A is downregulated in acute lymphoblastic leukemia patients, which is caused by epigenetic silencing." (PMID 26316480, 2015). "Loss of WNT-5A expression is reported in acute myeloid and acute lymphoblast leukemia." (PMID 26514730, 2016). "WNT-5A has been shown to be epigenetically silenced by promoter hypermethylation in acute lymphoblast leukemia cells leading to the loss of expression which may drive unrestricted B cell proliferation and malignant development." (PMID 26514730, 2016).
acute respiratory distress syndrome (2 papers, 2016 to 2019). Progressive and life-threatening pulmonary distress in the absence of an underlying pulmonary condition, usually following major trauma or surgery. "Increased amount of WNT-5A is observed in lung tissue from mouse model of acute respiratory distress syndrome (ARDS) which could be the repair response of damaged lungs to resolve the injury." (PMID 26514730, 2016).
acute T-cell leukemia (2 papers, 2016 to 2017). "In another example, high expression of WNT-5A is observed in the PBMCs derived from acute T-cell leukemia/lymphoma (ATL) patients." (PMID 26514730, 2016).
adenomyosis (2 papers, 2020 to 2022). The growth of endometrial tissue inside the muscular wall of the uterine corpus. "Unlike for the low expression of gene products from hypermethylated PAX8 and WNT5A in adenomyosis, the IHC staining results revealed inconsistent trends in higher protein expression." (PMID 35682653, 2022). "WNT5A exhibited weak-to-moderate expression in both the gland and stromal cells in the adenomyosis and control groups (the proportions of high expression: adenomyosis, 30%; control, 14%; p = 0.45)." (PMID 35682653, 2022). "Wnt pathway activation induces EMT in several tissues; we found that WNT5A mRNA was differentially expressed in the endometrium of adenomyosis patients." (PMID 32719721, 2020). "WNT5A may contribute to the pathogenesis of adenomyosis through proliferation of epithelial and fibroblast cells and regulation of vasculature development." (PMID 32719721, 2020). "Thus, WNT5A may contribute to the pathogenesis of adenomyosis but is not regulated through the regulation of m6A RNA methylation regulators." (PMID 32719721, 2020).
airway hyperresponsiveness (2 papers, 2016 to 2019). "In airway smooth muscle cells, WNT5A is associated with remodeling in a context of airway hyperresponsiveness." (PMID 31558434, 2019). "Even in the absence of changes directly related to contractile function, based on our findings changes in the expression of WNT-5A may affect ASM contractility and contribute to airway hyperresponsiveness." (PMID 27468699, 2016).
allergic disease (2 papers, 2016 to 2023). An immune response that occurs following re-exposure to an innocuous antigen, and that requires the presence of existing antibodies against that antigen. "Consequently, Wnt5a may be a potential therapeutic target in allergic diseases." (PMID 27843938, 2016).
ameloblastoma (2 papers, 2020 to 2025). The most common odontogenic tumor, arising from the epithelial component of the embryonic tooth and usually affecting the molar-ramus region of the mandible or maxilla. "Previous study referred that Wnt5a activation could promote ameloblastoma cell migration." (PMID 32742496, 2020).
anorectal malformation (2 papers, 2022 to 2024). "The circRNA Rno_circ_0005139 was found to influence cell proliferation and apoptosis by acting as a miR-324-3p sponge, thereby downregulating Wnt5a in a rat anorectal malformation." (PMID 36434735, 2022).
autoimmune myocarditis (2 papers, 2017 to 2020). Autoimmune myocarditis is an autoimmune disease that affects the heart. "During cardiac fibrosis resulting from autoimmune myocarditis, Wnt1 and Wnt5a expression is induced in regions of immune cell infiltration, and inhibition of Wnt signaling via administration of soluble pathway inhibitors prevents cardiac fibrosis and improves cardiac function." (PMID 28959037, 2017).
bladder tumor (2 papers, 1998 to 2024). "Wnt5a and Wnt7b mRNAs were both expressed in normal bladder tissues and bladder tumours." (PMID 9461004, 1998).
brain tumor (2 papers, 2012 to 2013). "One exception is brain tumors and metastases, which have been associated with overexpression of WNT-5A." (PMID 22647544, 2012).
ciliopathies (2 papers, 2014 to 2016). "WNT-5A signaling has also been implicated in ciliopathies and WNT-5A antagonism counteracts vascular calcification." (PMID 26514730, 2016). "WNT-5A signaling has also been implicated in ciliopathies and WNT-5A antagonism has been shown to counteract vascular calcification." (PMID 24728340, 2014).